CCDC89 (coiled-coil domain containing 89)
Synonyms: FLJ38159
Tractability: No criterion of Open Targets' tractability assessment is met for any kind of drug.
Gene: Protein-coding gene on chromosome 11 (85,683,848 to 85,686,195, reverse strand). Ensembl gene ENSG00000179071.
Subcellular location: Cytoplasm; Nucleus
Subcellular location (Human Protein Atlas): Nucleoplasm
Gene Ontology:
Molecular function: protein binding
Cellular component: cytoplasm; nucleus
Genetic constraint (gnomAD): Loss-of-function variants: 28 observed, 29.83 expected, observed/expected ratio (o/e) 0.94, 90% interval 0.69 to 1.29. The upper end of that interval is the gene's LOEUF score, 1.29, which puts it in group 5 of 6, group 1 being the genes least tolerant of losing a copy. Missense variants: 484 observed, 466.04 expected, observed/expected ratio (o/e) 1.04, 90% interval 0.96 to 1.12. Synonymous variants: 191 observed, 190.35 expected, observed/expected ratio (o/e) 1, 90% interval 0.89 to 1.13.
Homologues: Orthologues: chimpanzee CCDC89 (99% identical), macaque CCDC89 (95% identical), dog CCDC89 (82% identical), pig CCDC89 (81% identical), rabbit CCDC89 (80% identical), rat Ccdc89 (78% identical), mouse Ccdc89 (77% identical).